LEP (leptin)
Diseases named in the same sentence as LEP in open-access papers (continued):
Sharing a sentence is not in itself a finding about the gene and the disease.
tumor (continued). "Because both leptin and IL-1 are inflammatory and pro-angiogeneic factors that upregulate VEGF, we hypothesised that the association between IL-1 and leptin could be a critical event for tumour angiogenesis." (PMID 21139583, 2011). "However, perhaps due to the relative small sample of tumors analyzed, we were unable to detect any associations between leptin/ObR and either tumor grade, ERα/PgR, or metastasis, reported by different authors previously." (PMID 18945363, 2008). "Leptin (LEP) has been consistently associated with angiogenesis and tumor growth." (PMID 16504019, 2006). "Changes in the leptin–adiponectin ratio underline the importance of interplay of both adipokines—the imbalance between these adipokines, as well as interactions with the tumor microenvironment and other carcinogenic factors, may play a role in tumorigenesis and aggressiveness programming in PanNENs." (PMID 37444627, 2023). "Moreover, in vivo experiments showed that leptin may enhance antitumor effects as it increased M1-like tumor-associated macrophage frequency compared with non-leptin-treated mice." (PMID 35326405, 2022). "A study examining the expression level of leptin, which causes increased breast cancer development showed that it accelerates the PC process by activating the Notch signaling pathway associated with tumor metastasis and CSC differentiation in BxPC-3, MiaPaCa-2, Panc-1 and AsPC-1 PC cells." (PMID 37529006, 2022). "Interestingly, leptin signaling is linked to tumor development in various types of tissues." (PMID 30224299, 2018). "Likewise, the A allele of LEP G2548A is associated with the size of the tumor." (PMID 30404206, 2018). "However, a direct cause and effect role of leptin in accelerating tumor growth is uncertain." (PMID 21338489, 2011). "In its subnetwork, leptin is linked to HIF‐1α, IL‐1β, and IL‐6, suggesting some influence over the control of those drivers' downstream effects such as EMT and tumor invasion." (PMID 41450167, 2026). "A deeper understanding of these interactions is crucial for designing combinatorial strategies to effectively disrupt leptin-driven tumor aggressiveness." (PMID 41562922, 2026). "Beyond its metabolic roles, leptin also promotes angiogenesis and endothelial cell migration within the tumour microenvironment." (PMID 41498391, 2026). "In contrast to the generally held view, the authors reported that that fructose inhibited tumor growth and induced leptin secretion from adipocytes by activating mTORC1 in white adipose tissue cells." (PMID 40549205, 2025). "Although incompletely studied, PRAT-derived leptin imbalance in the tumor microenvironment has been recently noticed in several studies." (PMID 40227577, 2025). "Leptin, thus, acts as a pleiotropic mitokine, coordinating energy-sensing, redox adaptation, apoptosis resistance, and vascular remodelling within the tumour microenvironment." (PMID 41586225, 2025). "Excessive leptin levels have a dual role, potentially promoting angiogenesis and tumor progression or enhancing immune function and improving tumor burden resolution." (PMID 40072060, 2025). "According to the same study results, PRAT area expansion has been associated with VEGFA, JAG1, and TGF-β1 pro-angiogenesis gene expression increases, suggesting a possible interplay between PRAT-derived leptin activity and tumor angiogenesis." (PMID 40227577, 2025). "Long-term exposure to leptin increases tumour cell viability and shifts the mitochondrial phenotype toward apoptosis evasion and aerobic glycolysis, enabling anabolic growth in nutrient-variable microenvironments." (PMID 41586225, 2025). "Taken together, these results demonstrated that Rha suppresses leptin-induced aggressive tumor phenotypes, such as invasiveness and VM, in TNBC cells." (PMID 41463012, 2025).
tumor (continued). "Unhealthy obese WAT affects circulating levels of free fatty acids and factors like leptin, adiponectin, and insulin, altering systemic lipid metabolism and inducing inflammation that supports tumor growth." (PMID 39496581, 2025). "Explorations have confirmed the contact between adiponectin/leptin balance and mitogenesis, tumor growth, and cellular motility processes during adipose tissue dysfunction." (PMID 41164182, 2025). "Adipokines, such as leptin and resistin, stimulate tumor growth, while reduced adiponectin removes protective anti-inflammatory effects." (PMID 40732935, 2025). "Adipocytes, abundant in breast tissue, significantly influence tumor growth by supplying free fatty acids, cytokines, like leptin and IL-8, and pro-inflammatory signals that fuel tumor metabolism and invasion." (PMID 40333213, 2025). "As a lipoprotein enzyme, leptin is directly related to the proliferation and apoptosis process of tumor cells and promotes angiogenesis within tumor tissues through signaling pathways." (PMID 39980561, 2025). "For example, adipocyte-derived leptin and IL-6 can promote breast cancer cell metastasis by increasing the expression of lysyl hydroxylase (an enzyme in collagen synthesis) in tumor cells." (PMID 40863244, 2025). "As a crucial endocrine organ, adipose tissue regulates tumor behavior, inflammation, and the tumor microenvironment through adipokines, including leptin, adiponectin, as well as chemokines." (PMID 40620232, 2025). "In conclusion, subcutaneous fat contributes directly or indirectly to the development and progression of BC through various mechanisms, including inflammatory responses, leptin signaling, tumor microenvironment remodeling, and hypoxia induction." (PMID 40165893, 2025). "MMP2 and MMP9 produced by tumor cells are controlled by adipocyte-derived leptin and IL6 by activating FAK- and SRC-dependent pathways." (PMID 40841364, 2025). "Strikingly, we also observed that OB EVs and leptin promote mitochondrial redistribution toward membrane protrusions, an event crucial in facilitating tumor cell migration." (PMID 40485730, 2025). "A key area of interest is visfatin’s interaction with other adipokines (e.g., leptin, resistin, chemerin) and their combined effects on tumor progression." (PMID 40282553, 2025). "Leptin can activate signaling pathways in tumor cells, promote cell proliferation and resist apoptosis." (PMID 40969280, 2025). "One study on FMCs evaluated leptin and its receptor (ObR) in both tumor tissues and corresponding serum samples." (PMID 41150099, 2025). "There is evidence that leptin promotes tumour cell proliferation in a variety of cancer cell types, and its elevated levels have been associated with several neoplasms, including breast, colorectal and thyroid cancers." (PMID 41471707, 2025). "Various cytokines, such as IL‐1, IL‐6, and TNF‐α, as well as adipokines such as leptin and adiponectin, significantly impact tumor cell proliferation and invasion." (PMID 39652453, 2025). "On the one hand, obese patients have excessive adipose tissue, which can secrete a variety of cytokines and hormones, such as leptin and adiponectin, which regulate the growth, proliferation and invasion of tumor cells." (PMID 40969280, 2025). "It has been reported that dietary fructose initiated adipocytes to produce leptin in a mTORC 1-dependent manner, and mediated leptin to enhance the anti-tumor function of CD8+ T cells, which provided a reference for inhibiting tumors through leptin." (PMID 41200178, 2025). "In contrast to leptin, adiponectin levels are reduced in obese individuals, a response that is beneficial for tumor growth." (PMID 39496581, 2025).
tumor (continued). "In parallel, adipokines such as leptin and interleukin-6, upregulated under hypoxic conditions, promote tumor progression and facilitate immune evasion." (PMID 41323785, 2025). "Adipocyte-derived leptin acts on CD8+ T cells to enhance the anti-tumor activity of CD8+ T cells to control transplanted lung tumors." (PMID 40549205, 2025). "In a study conducted by Favreau and colleagues, the effects of leptin on anti-tumor immunity were explored within a murine model of MM." (PMID 40565082, 2025). "For instance, dysfunctional adipose tissue elevates the production of the pro-inflammatory mediator leptin while reducing levels of adiponectin, an adipokine with anti-inflammatory and anti-tumor properties." (PMID 41269404, 2025). "The level of expression of adiponectin and leptin correlates with the difficulty of surgical dissection as well as the tumor differentiation." (PMID 41255618, 2025). "Using a proteome profiler array, we identified the adipokine leptin as an inducer of ADAMTS13 in tumor cells." (PMID 41211185, 2025). "Circulating levels of oxidized low-density lipoprotein (oxLDL), prostaglandin E2 (PGE2), and leptin are emerging as markers of lipid-mediated inflammation and immunosuppression in the tumor microenvironment." (PMID 40487761, 2025). "As a potential mechanism of action, higher levels of angiogenic factors such as VEGF, IGF-1 or leptin were observed in obese patients, leading to chemoresistance and enhanced tumor proliferation." (PMID 40217461, 2025). "Their findings illustrated not only elevated levels of leptin and its receptor but also a disturbing interference with the anti-tumor functions of invariant natural killer T cells (iNKT), which are crucial for immune response." (PMID 40565082, 2025). "In vitro, leptin stimulation increases cellular migration, and in vivo, in murine models, depletion of the leptin receptor reduced orthotopic tumor growth in obese mice." (PMID 40940878, 2025). "Leptin promotes tumor growth by activating the JAK/STAT and PI3K/AKT signaling pathways, leading to increased proliferation, angiogenesis, and inhibition of apoptosis." (PMID 41010935, 2025). "Recent studies have reported that leptin promotes tumor progression through mechanisms such as cell proliferation, survival, and angiogenesis." (PMID 40565190, 2025). "Leptin promotes tumor angiogenesis by upregulating HIF-1α and VEGF, Conversely, adiponectin deficiency leads to reduced expression of anti-angiogenic factors (e.g., thrombospondin-1), further exacerbating vascular abnormalities." (PMID 41164182, 2025). "Leptin, produced and secreted by WAT into circulation, with the induced PD‐1 subsequently suppressing tumor‐associated macrophage metabolic activity." (PMID 41306337, 2025). "Leptin stimulates tumor proliferation and epithelial–mesenchymal transition via JAK2/STAT3 signaling." (PMID 41164182, 2025). "Specifically, the authors in this study found that dietary fructose increased adipocyte-derived production of leptin, a hormone that is critical for T cell-mediated anti-tumor immunity." (PMID 38711514, 2024). "These vesicles also carry leptin and key miRNAs (miR-155-5p, miR-10a-3p, miR-30a-3p, miR-32a/b, miR-21), thereby supporting tumor cell proliferation, metastasis formation, and therapy resistance." (PMID 39697630, 2024). "Some studies have indicated that leptin can be secreted by tumor-stromal adipocytes (TSAs) stimulated by external conditions and bind to receptors on tumor cells, resulting in proliferation, invasion and other effects." (PMID 39192979, 2024). "Resulting oxidative stress can in turn drive endothelial dysfunction due to reduced NO bioavailability, and also can be compensated for by leptin-mediated angiogenesis to re-establish tissue (or tumor) blood flow and support metabolic waste removal." (PMID 39439572, 2024). "Further, higher leptin and lower adiponectin, observed in the high-adiposity phenotypes, play important roles in immune suppression and tumor progression." (PMID 39575261, 2024).
tumor (continued). "Leptin plays a pro-tumor role, and on the other hand, adiponectin, an anti-inflammatory adipokine, has been shown to exert an anti-tumor effect." (PMID 38791037, 2024). "An important target of JNK signaling in the tumor is cytokine Upd2/leptin, normally produced and released from the adipose tissue, the fat body, to induce the release of insulin-like peptides to regulate systemic growth." (PMID 39642218, 2024). "Similar to other reports, we demonstrate that leptin promoted tumor characteristics of malignancy such as mesenchymal-like cell morphology and increased proliferation in hormone receptor-positive cells but not in triple-negative cells." (PMID 38228661, 2024). "Intriguingly, leptin not only promotes tumor progression by regulating angiogenesis, inhibiting apoptosis, and remodeling the TME but also plays a critical role in antitumor immunotherapy through innate and adaptive immune response." (PMID 38405061, 2024). "Leptin, a key adipokine, activates survival and proliferative signaling pathways whereas adiponectin exhibits tumor-suppressive effects by inducing apoptosis and cell cycle arrest." (PMID 38255203, 2024). "Leptin-induced aromatase expression also occurs in adipose stromal cells within the tumor microenvironment." (PMID 39439572, 2024). "In esophageal squamous cell carcinoma, leptin expression correlates with lymph node involvement and tumor stage." (PMID 38255203, 2024). "In these contexts, the role of leptin in driving EMT contributes significantly to the enhancement of cell invasion and migration, ultimately underscoring the profound effect of leptin on the metastatic potential of tumor cells." (PMID 38255203, 2024). "Some studies have shown that leptin has oncogenic activity via activation of the PI3K/Akt pathway and signal transducer and activator of transcription (STAT) 3 and STAT5 in tumor cells, whereas adiponectin inhibits leptin-associated pathways." (PMID 38275895, 2024). "Adiponectin can counteract the effects of leptin, exerting an antitumor effect by inhibiting angiogenesis, cell proliferation, tumor invasion, and metastasis." (PMID 38405061, 2024). "This alteration in Treg function promoted HCC growth in the graft model, highlighting the crucial role of leptin signaling in regulating anti-tumor immunity in vivo." (PMID 39061246, 2024). "Adiponectin’s role in the tumor microenvironment contrasts with that of leptin, sparking debate over its impact on cancer." (PMID 38571500, 2024). "This is a critical effect of leptin on tumor blood vessels in adipose tissue but is beyond the scope of the present review." (PMID 39439572, 2024). "Leptin can bind to receptors on tumor cells and trigger effects on proliferation, migration, and tumor invasion." (PMID 38672455, 2024). "In some cases, reductions in leptin levels have been reported after surgical lesions’ excision probably due to a direct secretion by the tumor mass." (PMID 39722796, 2024). "Leptin is an adipokine secreted by adipose tissue, which promotes tumor progression by activating canonical signaling pathways such as MAPK/ERK." (PMID 38228661, 2024). "Wang and colleagues showcased that in diet‐induced obese (DIO) mice, there was a notable increase in exhausted T cells via leptin pathway, ultimately promoting tumor progression and metastasis." (PMID 38334504, 2024). "The findings suggest that GITR, along with other immunosuppressive markers, plays a crucial role in mediating the effects of leptin on Treg function, ultimately influencing the balance between immune suppression and anti-tumor immunity in HCC." (PMID 39061246, 2024). "Leptin, Adiponectin, Nesfatin-1, Resistin, Chemerin, Visfatin: Mechanisms of action in tumor bone metastasis - Literature table." (PMID 38571500, 2024). "In recent decades, Cel has been shown to have pharmacological activities, including sensitizing leptin, anti-inflammatory effects, and anti-tumor properties." (PMID 39309437, 2024).
tumor (continued). "Leptin has the potential to affect the tumor microenvironment through various mechanisms, resulting in tumor invasion and distant metastasis." (PMID 38255203, 2024). "Remarkably, these tumor cells mimic adipocytes by sending the Upd2/leptin signal to regulate insulin release, thereby controlling tumor growth." (PMID 39642218, 2024). "It has been reported that leptin can modify the process of autophagy and favor leptin-driven tumor development and growth." (PMID 38228661, 2024). "The patients with the primary tumor location within the small intestine (SINETs) showed lower leptin levels than those of patients with other tumor locations (4.9 ± 6.49 vs. 11.97 ± 9.7, p = 0.018)." (PMID 39337308, 2024). "CR and PF have an anti-tumor effect in acute lymphocytic leukemia (ALL) by decreasing leptin levels." (PMID 38473997, 2024). "Previous research has indicated that overexpression of leptin and leptin receptors significantly affect tumor proliferation, invasion, and metastasis, accelerating the process of tumor deterioration and decrease the survival rates." (PMID 38405061, 2024). "Proteins with roles in angiogenesis (such as ferritin, CA15-5, and leptin) are likely to be carried by EVs from tumor cells to endothelial cells." (PMID 37857666, 2023). "CAAs can also promote tumor cell invasion by upregulating the levels of versican and leptin in renal cancer cell lines." (PMID 37666813, 2023). "OV has been engineered to enforce leptin expression to reprogram tumor-infiltrating T-cell metabolism, thereby promoting tumor clearance." (PMID 37009515, 2023). "Overall, leptin is associated with a STAT3-mediated metabolic reprogramming of CD8+ T-cells, which compromises their anti-tumour properties." (PMID 37173907, 2023). "Numerous adipokines have been identified; however, we will focus on the ones that have the best-documented role in neoplasia and are primarily secreted by adipocytes, such as leptin and adiponectin." (PMID 37626804, 2023). "Next, the inhibitory effect of SM and its derivatives on key pro-tumor characteristics of leptin-stimulated Neuro2a cells was studied." (PMID 37895840, 2023). "Further qRT-PCR showed leptin was highly induced in eWAT and iWAT from mice receiving 10A/miR-204 sEVs or tumour-bearig mice compared to their respective control groups." (PMID 37620316, 2023). "Similar to the results of the analysis with regard to Ki-67% and tumor grading, patients with distal disease presented lower leptin concentration and decreased leptin–adiponectin ratio." (PMID 37444627, 2023). "Of the FMC subtypes, luminal B and triple-negative subtypes were observed to have the greatest tumor expression of leptin, while luminal B and HER2-positive subtypes were found to have the lowest serum leptin levels." (PMID 37626804, 2023). "In breast cancers, adipocytes enhance CSC properties and tumor proliferation through signaling pathways like NF-κB, Wnt, and Notch, by secreting leptin, visfatin, and resistin." (PMID 37784157, 2023). "Leptin promotes cell proliferation and angiogenesis, while adiponectin has anti-inflammatory and anti-tumor properties." (PMID 37834153, 2023). "The accumulation of HIF1α promotes the induction of several gene targets, such as leptin and ObRs, in adipocytes, fibroblast and tumor cells." (PMID 37686525, 2023). "Leptin induces tumor dissemination and metastasis of BCCs to bone tissue by activating the SDF-1/CXCR4 axis, and upregulation of CXCR4 contributes to bone metastasis and poor survival." (PMID 37686525, 2023). "Studies have shown that leptin plays an important role in dysmetabolic conditions, immunological functions, and tumor progression." (PMID 36811728, 2023). "Multivariate regression analysis revealed that BMI, leptin, IL-6 and reactive oxygen species were predictive factors for tumour size, lymph node stage and metastasis status in ER+ patients." (PMID 37173907, 2023).